BRCA1 (BRCA1 DNA repair associated)
Diseases named in the same sentence as BRCA1 in open-access papers (continued):
Sharing a sentence is not in itself a finding about the gene and the disease.
ovarian carcinoma (continued). "The acquisition of BRCA1/2 reversion mutations was closely related to resistance to therapy and may be beneficial to predict the chemotherapy response of ovarian cancer, guiding the treatment of ovarian cancer." (PMID 33936202, 2021). "Hereditary breast and ovarian cancer is caused by a germline mutation in BRCA1 or BRCA2 genes." (PMID 34356066, 2021). "Other potentially deleterious missense mutations in LD with ALT-increasing alleles were found in ANO5, which is associated with Miyoshi muscular dystrophy; the breast/ovarian cancer susceptibility gene BRCA1; and LRBA, associated with common variable immunodeficiency." (PMID 33547301, 2021). "Finally, in observational studies patients with ovarian cancer or predisposition for ovarian cancer (germline BRCA1 mutation) were associated with a specific microbiome in the vagina/cervix." (PMID 33807612, 2021). "Rare variants in several genes that were initially implicated in risk for breast or ovarian cancer predisposition (e.g., BRCA1, BRCA2, CHEK2, BRIP1, and ATM), as well as the mismatch repair (MMR) genes, have also been reported to increase the risk of prostate cancer." (PMID 33804961, 2021). "Thus, the treatment of ovarian cancer patients can be divided into two groups based on the mutational status of BRCA1/2." (PMID 35071013, 2021). "The genetic basis for ovarian cancer predisposition was originally established with the identification of BRCA1 (OMIM# 113705) and BRCA2 (OMIM# 600185), which are both tumor suppressor genes implicated in the mechanism of Homologous Recombination (HR) repair of DNA double-strand breaks." (PMID 34898566, 2021). "Additionally, BRCA1/2 mutations are related to increased susceptibility to endometrial and ovarian carcinoma." (PMID 34837690, 2021). "The BRCA1/2 mutations could be detected in the ctDNA from ovarian cancer patients, which responded well to the targeted therapy of the PARP1 inhibitors." (PMID 33936202, 2021). "Importantly, the BARD1-CA125 261-sample-fitted model reached a sensitivity of 0.99 for the no-mutation (wt) and “other” groups (other than BRCA1/2 or BARD1 group of OC) and a sensitivity of 1 for the ovarian cancers with BRCA1/2 or BARD1 mutations." (PMID 34201956, 2021). "The oral contraceptive pill is known to reduce the risk of sporadic endometrial and ovarian cancer, as well as BRCA1/2‐associated ovarian cancer, and the levonorgestrel‐releasing intrauterine system reduces the risk of endometrial cancer in the general population." (PMID 33679238, 2021). "The uterine and ovarian cancer association may be explained by either a mutation or an overexpression of BRCA1/BRCA2, and by MMR genes." (PMID 34556087, 2021). "Evaluation of families with multiple cases of breast and/or ovarian cancer have demonstrated an approximate 40% mutation frequency in the BRCA1/2 genes, suggesting less prevalent germline mutations contribute to the development of hereditary breast and ovarian cancer." (PMID 33419231, 2021). "The potential risk of endometrial cancer should be considered and discussed with the patient, in relation to the advantages and the risk of also having a hysterectomy at the time of the risk-reducing surgery for ovarian cancer in women with a deleterious mutation of the BRCA1 gene." (PMID 34547799, 2021). "As we also found higher PAF-AH levels in BRCA1 mutation carriers and BRCA1 mutant ovarian cancer cells, we conclude that PAF-AH upregulation might be relevant to counteract PAF and Wnt signaling, respectively." (PMID 34206491, 2021).
ovarian carcinoma (continued). "In a population-based cohort and a screening trial of individuals at high risk of ovarian cancer, both RAD51C and RAD51D were shown to be moderately susceptible to ovarian cancer, suggesting the usefulness of these genes alongside BRCA1/2 for the prediction of susceptibility to ovarian cancer." (PMID 34838098, 2021). "Through the GEMO study, blood DNA from BRCA1/2 mutation carriers is available to perform genetic epidemiological projects aiming at identifying and characterizing genetic factors modifying breast and ovarian cancer risk." (PMID 34325649, 2021). "In our previous study, we observed BRCA1 founder mutation only in 16% of ovarian cancer patients." (PMID 33478551, 2021). "The discovery of BRCA1/2 mutations is one of the milestones in the treatment of ovarian cancer." (PMID 35071013, 2021). "Beyond the cellular function, we aimed to assess a possible influence of PAF-AH on the Wnt signaling pathway for a better understanding of ovarian cancer pathophysiology, taking into account differences between BRCA1 mutation carriers and BRCA wildtype (WT) patients." (PMID 34206491, 2021). "Furthermore, genetic counseling and testing for BRCA1/2 mutations should be offered to all newly diagnosed patients, as it was estimated that 18% of ovarian cancer cases were associated with germline mutations, mostly of the BRCA1/2 genes." (PMID 33800101, 2021). "Besides, another study confirmed a BRCA1/2 mutation rate of 39.2% (107/273) in ovarian cancer patients with stage IIIC-IV, which was consistent with our findings." (PMID 35071013, 2021). "BRCA1 is a tumor suppressor gene which encodes a nuclear protein that can maintain genome integrity, and germline mutations of the BRCA1 gene are responsible for most familial cases with breast and ovarian cancer." (PMID 34926299, 2021). "Rucaparib was first indicated for the treatment of advanced ovarian cancer with either germline or somatic BRCA1/2 mutations, and was then approved in 2018 for the maintenance treatment of platinum‐sensitive ovarian, fallopian tubal, and peritoneal cancer regardless of the BRCA status." (PMID 34977872, 2021). "In addition, we estimated the risks of breast or ovarian cancer for BRCA1/2 carriers by mutation regions." (PMID 34063308, 2021). "Second, HR deficiency may occur in epithelial ovarian cancer via multiple mechanisms, including BRCA1/2 mutations." (PMID 34869593, 2021). "In Central-Eastern European counties, the founder mutations in the BRCA1 are responsible for a significant proportion of ovarian cancer cases, however, regional differences in the frequencies of various mutations may exist." (PMID 33478551, 2021). "BRCA1-C61G is a founder mutation in the Polish population and is included in standard panel tests for the diagnosis of hereditary cancer and for the treatment of breast and ovarian cancers in Polish patients." (PMID 36860287, 2021). "A large genome-wide association study (GWAS) and meta-analysis of sporadic epithelial ovarian cancer cases, BRCA1 and BRCA2 carriers (15,252 and 8211 respectively) and 30,845 healthy controls identified genomic variants of Wnt pathway components, Wnt4 and RSPO1 genes, as new susceptibility loci." (PMID 34283069, 2021). "Two identified biomarkers among differentially expressed proteins, SPARC and THBS1, had lower plasma concentrations in healthy BRCA1/2 variant carriers than in ovarian cancer patients with the BRCA1/2 variant; concentration of two proteins increased at the onset of ovarian cancer." (PMID 34064977, 2021). "The common germline mutations in ovarian cancer includes BRCA1, BRCA2, ATM, MSH3 and PALB257." (PMID 33432021, 2021). "Dysfunction of BRCA1 leads to a high risk of breast and ovarian cancer for women." (PMID 33623049, 2021). "Consistent with the “incessant ovulation” hypothesis of ovarian cancer pathogenesis, a decreased risk of ovarian cancer has been demonstrated in the BRCA1/2 mutated and general populations who have used oral contraceptives." (PMID 33419231, 2021).
ovarian carcinoma (continued). "Most hereditary ovarian cancer is associated with BRCA1/2 variants, and risk-reducing salpingo-oophorectomy during the follow-up monitoring of ovarian cancer development in heathy women with the BRCA1/2 variant reduces ovarian cancer incidence." (PMID 34064977, 2021). "This is the third study of BRCA1 mutations in ovarian cancer patients from Belarus." (PMID 33478551, 2021). "Another study using ovarian cancer cells demonstrated that the sensitivity of the cells to auranofin is enhanced by BRCA1 deficiency; BRCA1 is involved in DNA repair and in regulating the stability of anti-oxidant transcription factor Nrf2 via protein–protein interaction." (PMID 35201489, 2021). "Consistent with the SOL1 Phase III clinical trial advanced ovarian cancer patients with BRCA1/2 mutations who experience remission after initial platinum-containing treatment could benefit from olaparib." (PMID 34837690, 2021). "However, even if having a BRCA mutation is a well-known risk factor, among individuals with OC (ovarian cancer), both BRCA1 and BRCA2-associated patients have better outcomes." (PMID 33435590, 2021). "Considering that we found increased TNBC percentage (around 3%) in patients with a family history of breast/ovarian cancer, and BRCA1 mutation is linked with increased TNBC percentage, common genetic mutations could potentially influence our results." (PMID 33737705, 2021). "Moreover, as much as half of the OCCC exhibited the BRCAness phenotype (mutation in 18 different HR genes or having BRCA1 hypermethylation or loss of BRCA1 protein expression) in a Danish ovarian cancer cohort comprising 20 cases of OCCC." (PMID 34737943, 2021). "In addition to breast and ovarian cancers, BRCA1/2 mutations increase risks for other cancer types, including pancreatic cancer, prostate cancer, and colorectal cancer." (PMID 34805171, 2021). "Wild-type BRCA1/2 genes are critical for DNA repair by the homologous recombination (HR) pathway; hence their deletion causes genomic instability and predisposes affected women to familial breast and ovarian cancers." (PMID 33800113, 2021). "For BRCA1, the risk of ovarian cancer at an early age has been well established." (PMID 33926482, 2021). "BRCA1/2 are the two major susceptibility genes for breast and ovarian cancers." (PMID 33842374, 2021). "Consequently, BRCA1 mutation carriers have a 40–60% risk of developing ovarian cancer in their lifetime, while BRCA2 mutation carriers’ cumulative risk is up to 25%." (PMID 34206491, 2021). "Predisposition of germline BRCA1/2 mutations (gBRCAMUT) increases the risk of breast and ovarian cancer in females, but the mutation prevalence and spectrum are highly ethnicity-specific with different recurrent mutations being reported in different populations." (PMID 34046351, 2021). "The chance of developing ovarian cancer if an individual has a BRCA1 mutation is 39–46%." (PMID 34711195, 2021). "A meta-analysis of 33 studies of patients with ovarian cancer showed that overall survival (hazard ratio = 0.75, p < 0.001) and progression-free survival (hazard ratio = 0.80) in the BRCA1/2 mutation cohort (p = 0.039) were significantly extended compared to that of patients with no BRCA mutation." (PMID 32862296, 2021). "Germline and somatic mutations in BRCA1 have been identified in approximately one‐third of ovarian carcinomas, and their presence is highly predictive of primary platinum and PARP (Poly‐ADP‐Ribose‐Polymerase) inhibitors sensitivity and favorable progression‐free and overall survival." (PMID 34601813, 2021). "Similarly, olaparib treatment reduced the granulocyte component of the MDSC population in a mouse model of breast cancer susceptibility genes 1 (BRCA1)-deficient ovarian cancer." (PMID 34885119, 2021). "The BRCA1/2 genes are the most commonly mutated genes in hereditary breast and ovarian cancers." (PMID 33498525, 2021).
ovarian carcinoma (continued). "Individuals at increased risk of breast and ovarian cancer associated with pathogenic variants in BRCA1/2 account for up to 10% of breast cancer cases, 15% of ovarian cancer cases, and up to 20% of cases of high-grade serous ovarian cancer, the most aggressive subtype." (PMID 34834546, 2021). "Interestingly, the frequency of BRCA1 germline mutations in Chinese is significantly higher than that in Western ovarian cancer patients, which also supported the different mutational patterns of ovarian cancer patients in different regions." (PMID 33432021, 2021). "The ovarian cancer risk was associated with mutations in BRCA1 (OR = 40.79, 95% CI: 18.67–114.78; p = 0.29 × 10−15), in BRCA2 (OR = 25.98; 95% CI: 1.55–434.8; p = 0.001), in RAD51C (OR = 6.28; 95% CI 1.77–39.9; p = 0.02), and in PALB2 (OR 3.34; 95% CI: 1.06–14.68; p = 0.06)." (PMID 33670479, 2021). "BRCA1-mutated ovarian cancer cells (UWB1.289) significantly overexpressed PAFR." (PMID 34571986, 2021). "Ovarian cancer screening in individuals with germline variants in BRCA1 or BRCA2 is contentious." (PMID 34771713, 2021). "Carriers of inherited pathogenic sequence variants (PSVs) in BRCA1 and BRCA2 are at an increased lifetime risk of developing ovarian cancer; recent reports highlighted that the cumulative risk of ovarian cancer to age 80 years was 44% for BRCA1 carriers and 17% (95% CI, 11-25%) for BRCA2 carriers." (PMID 34930165, 2021). "The most prominent progress in gynecologic cancers is the clinical efficacy of poly(ADP-ribose) polymerase (PARP) inhibitors, which have shown breakthrough benefits in reducing hazard ratios (HRs) (HRs between 0.2 and 0.4) of progression or death from BRCA1/2 mutated ovarian cancer." (PMID 34680987, 2021). "On average, the risk of cancer differs between the two genes, as for BRCA1 the assessed average risk of breast and ovarian cancers ranges from 57 to 65% and from 20 to 50%, respectively, and for BRCA2 the risk ranges from 35 to 57% and from 5 to 23%, respectively." (PMID 34026625, 2021). "Thus, to establish the diagnosis for targeted therapy in Pakistan, we conducted Next-generation sequencing-based germline testing for the detection of BRCA1/2 oncogenic variants associated with breast and ovarian cancer subtype." (PMID 33773534, 2021). "Ovarian cancer patients with germline BRCA1/2 mutations are sensitive to platinum-based therapies and demonstrate improved survival; however, if they develop a secondary somatic BRCA1/2 mutation, platinum-resistance ensues." (PMID 33419231, 2021). "BRCA1 is frequently mutated in familial breast and ovarian cancers." (PMID 32139898, 2020). "Finally, several studies showed the association between specific BRCA1/2 PVs and variations of breast and ovarian cancer relative risks." (PMID 32380732, 2020). "Poly-ADP ribose polymerase (PARP) inhibitors are currently used in the treatment of several cancers carrying mutations in the breast and ovarian cancer susceptibility genes BRCA1 and BRCA2, with many more potential applications under study and in clinical trials." (PMID 32183301, 2020). "BRCA1/2 mutation carriers are at a higher risk of developing ovarian cancer." (PMID 33322519, 2020). "Indeed, this is the case, as cancer cells with aberrant variants of BRCA1/2 such as breast and ovarian cancers are prone to cell death in the presence of PARP inhibitors, thereby demonstrating synthetic lethality." (PMID 32180937, 2020). "Comparing primary and recurrent ovarian cancers, it was shown that 13 out of 46 recurrent HGSOCs (28.3%, 95% CI 17.3–42.6%) had a secondary mutation and 2 out of 64 primary HGSOCs (3.1%, 95% CI 1.0–10.7%) in germline BRCA1/2 mutation carriers." (PMID 32833070, 2020). "Similar to ovarian cancer, the majority are caused by BRCA1/2 mutations." (PMID 33015058, 2020).
ovarian carcinoma (continued). "Hereditary breast and ovarian cancers are mainly linked to variants in BRCA1/2 genes." (PMID 32806537, 2020). "Altogether, these Manchester scores could indicate an intermediate cancer burden in families with BRCA1 c.5407-25T>A, higher than for average patients with breast and ovarian cancer, but lower than for families with truncating BRCA variants." (PMID 32203205, 2020). "Hence, genetic testing for BRCA1/2 mutations is recommended for all newly diagnosed ovarian cancer patients to aid in therapy selection and determining cancer risk for family." (PMID 33036656, 2020). "This phase II single-arm trial investigated the activity of 6MP 55–75 mg/m2 per day, and methotrexate 15–20 mg/m2 per week in advanced breast or platinum-resistant ovarian cancer patients with a BRCA1/2 germline mutation, who had progressed after ≥1 previous line of chemotherapy." (PMID 31813938, 2020). "About 10% of breast or ovarian cancer patients carry BRCA1/2 gene mutations." (PMID 33157956, 2020). "Hence, knowing the status of BRCA1/2 mutation in ovarian cancer patients is important in order to support a decision a clinician for selecting an appropriate treatment option for the patients." (PMID 32856869, 2020). "Interestingly, analyzing the tumor types occurring in DH and DM families, we observed ovarian cancer only in DH families, probably due to the presence in DH patients of BRCA1 pathogenic variants, which predispose one more to ovarian cancer onset." (PMID 33287145, 2020). "The lifetime risk of ovarian cancer was different between BRCA1 and BRCA2 mutation carriers." (PMID 32096544, 2020). "Rucaparib was cytotoxic to human cancer cell lines with mutated BRCA1/2 and was then found to be effective in a wide range of ovarian cancer cell lines (including homologous recombination pathway deficiencies not including BRCA1/2 mutations) alone and in combination with other agents." (PMID 33233320, 2020). "The ovarian cancer risk is 59–65% for the BRCA1 mutation and 34.5–37% for the BRCA2 mutation." (PMID 32322271, 2020). "An important role of BRCA1/2 testing is to identify high-risk variant carriers before they develop breast or ovarian cancer, so they may start cancer screening and preventive interventions to reduce cancer risk." (PMID 32028596, 2020). "Poly-(ADP Ribose) Polymerase (PARP) inhibitors (talazoparib, olaparib) has been recently approved for the treatment of breast and ovarian cancers with BRCA1/2 mutations, and several others drugs inhibiting or modulating DNA repair pathways are currently in clinical development for cancer therapy." (PMID 33036275, 2020). "The existence of intermediate-penetrance variants in high-risk genes has been described by the ENIGMA consortium; the missense variant c.5096G>A (p.Arg1699Gln) in BRCA1 has been demonstrated to be associated with a lower risk of breast and ovarian cancer than truncating variants." (PMID 32203205, 2020). "BRCA1 mutations are frequently identified in familial breast and ovarian cancers." (PMID 32139898, 2020). "Similarly, ~ 50% cases of high-grade ovarian cancers carry BRCA1 and BRCA2 mutations, causing high-incidence of homologous recombination deficiency (HRD)." (PMID 33087072, 2020). "Mutations in BRCA1/2 genes represent significant risk factors for breast and ovarian cancer." (PMID 32140806, 2020). "Therefore, tumor BRCA1/2 testing is a powerful tool to identify mutations in ovarian cancer patients which have been shown to benefit from treatment with PARP inhibitors." (PMID 32856862, 2020). "BRCA1/2 deleterious variants account for most of the hereditary breast and ovarian cancer cases." (PMID 32727387, 2020).